CRP (C-reactive protein)
Diseases named in the same sentence as CRP in open-access papers (continued):
Sharing a sentence is not in itself a finding about the gene and the disease.
Obesity (continued). "Our research conducted the first attempt to explore how the CRP-depression association varied across subjects with underweight, normal weight, overweight and obesity and to clarify how abnormal body weight moderates the depression-inflammation relationship." (PMID 28128231, 2017). "C-reactive protein (CRP) is an acute-phase protein that has been consistently associated with obesity." (PMID 28257085, 2017). "In WRA, elevated CRP was positively associated with obesity [body mass index (in kg/m2) ≥30] in 7 of 9 surveys." (PMID 28615263, 2017). "Specifically, we chose CRP because it is associated with systemic inflammation related to obesity and insulin resistance." (PMID 28253297, 2017). "In WRA, the factor that was most consistently associated with elevated CRP was obesity (significantly positively associated in 7 of 9 countries with data) as has been shown in many previous studies." (PMID 28615263, 2017). "CRP is an acute phase protein significantly associated with obesity, representing the most sensitive markers of inflammation and an independent risk for cardiovascular disease." (PMID 28176237, 2017). "Here we find that CRP, in a range well below the chronic levels understood to result from obesity, is positively associated with adiposity, even in very lean subjects." (PMID 28003312, 2017). "CRP is, however, also positively associated with several lifestyle factors, such as obesity, smoking, alcohol consumption, and high meat consumption." (PMID 27701463, 2016). "Target peptides for C-reactive protein (CRP) and adiponectin were synthesized because these proteins are also related to cancer risk diseases, such as inflammation and obesity." (PMID 27579675, 2016). "Previous studies have highlighted the causal effect of obesity on inflammation, and the effect directions are consistent with mediation of both the association with CRP and HDL-cholesterol by BMI." (PMID 27286809, 2016). "The association of LPS with obesity and inflammation was highlighted by the positive correlation with body fat percentage and high CRP levels." (PMID 27992443, 2016). "CRP is increased in individuals with an overlap to other risk factor pathways such as obesity, low social class, and smoking." (PMID 27051078, 2016). "We suggest inflammation plays a central role in this relationship, as obesity features increases in inflammatory mediators such as C-reactive protein and interleukin-6, and chronic inflammation has been linked to worse stroke risk and outcome." (PMID 27655337, 2016). "Recently, the Icelandic Sleep Apnea Cohort study interestingly revealed that OSA severity was an independent predictor of IL-6 and CRP levels, but interacted with obesity such that this association was found only in obese patients." (PMID 27684378, 2016). "IL-6 is a potent inducer for hepatic synthesis of CRP and other acute phase proteins in obesity and therefore leads to increased risk of cardiovascular disease." (PMID 26909479, 2016). "CRP is a typical systemic inflammatory marker and its increased levels were linked with obesity, blood pressure, and hyperlipidemia." (PMID 27980459, 2016). "One of the five PC metabolites, PC aa C38:5, is associated with a number of inflammation markers and adipokines associated with increased obesity and insulin resistance, including C-reactive protein (CRP) and resistin." (PMID 27249024, 2016). "Elevated CRP has also been associated with lifestyle factors such as obesity, unhealthy diet, cigarette smoking, and physical inactivity." (PMID 26771311, 2016). "Otherwise, there are studies suggesting that obesity is an inflammatory status associated with the increase of some proinflammatory cytokines such as IL 6 and IL 8, but also with the blood level of C-reactive protein." (PMID 27015185, 2016). "Obesity related metabolic syndrome is associated with increase in the levels of a number of markers of inflammation especially CRP." (PMID 27275343, 2016).
Obesity (continued). "CRP has been well described as associated with obesity and several features of the metabolic syndrome." (PMID 27111539, 2016). "Obesity was associated with higher sICAM-1 (p≤0.015), tumor necrosis factor-α (TNFα), interleukin-6 (IL-6), and high-sensitivity C-reactive protein (hs-CRP), p<0.001." (PMID 27459718, 2016). "Adherence to the ‘high-fat/low-fibre’ dietary pattern showed a strong positive associationwith current smoking, heavy drinking, physical inactivity, manual social class, obesity,total energy intake, CRP and vWF and an inverse association with HDL." (PMID 27620002, 2016). "The increase in the sum of skinfold thicknesses by 1 standard deviation (SD) was associated with higher odds of obesity and central obesity, metabolic syndrome, hyperglycaemia or type 2 diabetes, and elevated level of high-sensitivity CRP in adulthood." (PMID 25880559, 2015). "The effect of obesity, of causing chronic low-grade inflammation with an elevation of inflammatory markers (such as CRP, TNF-α, and IL-6) that increase the risk of cardiovascular disease, is even more pronounced in PCOS." (PMID 26124830, 2015). "In our previous study, the result indicated that obesity is associated with the level of CRP, but the associations of other metabolic disorders and the level of CRP were not reported in the study." (PMID 26193292, 2015). "This elevation of CRP in PCOS is more pronounced when obesity is present, further heightening the risk of cardiovascular events in this group of women." (PMID 26124830, 2015). "In diabetic patients, increasing high sensitive CRP levels correlated with severity of DR and the association was more pronounced in patients with BMI ≥ 30 kg/m 2 indicating that obesity imposes diabetic patients to more severe DR due to inflammatory process." (PMID 26644890, 2015). "We observed a positive association between CRP levels and obesity measures (BMI or WHR) in univariate linear regression model." (PMID 25650665, 2015). "Several studies have shown that obesity is associated with elevated serum levels of a wide range of inflammatory markers including C-reactive protein (CRP), interleukin 6 (IL-6), interleukin 8 (IL-8), and monocyte chemoattractant protein 1 (MCP-1)." (PMID 25972622, 2015). "Studies have demonstrated an association between CRP and obesity, between CRP and MS, or between other inflammatory markers and visceral obesity in OSA patients." (PMID 25586501, 2015). "In our study, the sum of subscapular and triceps skinfold thicknesses in childhood was associated with odds of obesity and central obesity, metabolic syndrome, hyperglycaemia or type 2 diabetes, and elevated high-sensitivity CRP in adulthood." (PMID 25880559, 2015). "In a study of obese diabetic patients there was a relationship between waist circumference and serum CRP levels suggesting an association between obesity and inflammation." (PMID 26644890, 2015). "Obesity is also a contributing factor; in obese women adiposity is associated with increased concentrations of inflammatory markers (IL-6, CRP, and adipokines) that correlate with depression and anxiety." (PMID 26089771, 2015). "At baseline, 1007 children had CRP and anthropometric data [mean (SD) age: 5.3 (2.9) years; 50.9% male, 84.5% mulatto/mixed-race, 14.0% at risk for overweight or obesity, 4.8% stunted]; 737 were successfully followed up." (PMID 24603645, 2014). "Associations between CRP and several measures of obesity and abdominal adiposity have been shown in a number of studies, and some studies indicate that abdominal adiposity has a stronger association with inflammation than total adiposity." (PMID 24681553, 2014). "Using only salivary CRP and insulin as predictors, the overall diagnostic sensitivity for identifying obesity by biomarker status was 89% and specificity was 61%." (PMID 24915044, 2014). "In a recent systematic review and meta-analysis, obesity was strongly associated with elevated levels of CRP in all populations observed." (PMID 25276234, 2014).
Obesity (continued). "Elevated CRP has also been associated with lifestyle risk factors such as obesity, physical inactivity, cigarette smoking, and alcohol consumption." (PMID 25268956, 2014). "We have identified five new CRP-mfs out of which CRP-mf-4 was significantly associated with obesity." (PMID 25299074, 2014). "Recent studies have confirmed positive association between obesity indices and inflammatory markers, mainly c-reactive protein (CRP) and other inflammatory cytokines." (PMID 24932457, 2014). "The significant association between CRP-mf-4 and obesity suggests that fat cells release some factor(s), which controls the formation of CRP-mfs." (PMID 25299074, 2014). "Future investigation is required to illustrate the differences in gender and CRP as it is associated with obesity in females and males to further clarify the importance of this inflammatory marker in cardiovascular and associated risk factors." (PMID 24944619, 2014). "Whilst studies investigating the association between CRP and adiposity are widespread in various populations, the association between leptin and obesity appears to be more complex." (PMID 24944619, 2014). "Data from 51 cross-sectional studies show that obesity is associated with elevated levels of CRP, and the association is stronger in women." (PMID 24955583, 2014). "Adipocytokines, such as adiponectin and C-reactive protein, and leptin are inflammatory proteins that have been linked to obesity and type 2 diabetes." (PMID 25208549, 2014). "Insulin resistance linked to obesity is a major risk factor for type 2 diabetes and cardiovascular disease and CRP is an inflammatory marker associated with CV disease in obesity." (PMID 25198070, 2014). "The different strength of the association of PI/I values with obesity and CRP levels in men and with IL-6 in women is difficult to be interpreted and would be likely clarified at the follow-up analysis." (PMID 25347846, 2014). "For example, in the British 1958 Birth Cohort the associations between obesity (body mass index, waist circumference), blood pressure, blood lipids, metabolic syndrome and CRP were twice as strong among women as among men." (PMID 25309988, 2014). "Adipose tissue mass accumulation in the visceral region during obesity has been associated with elevated levels of inflammatory mediators, including serum C-reactive protein (CRP), acute phase proteins and pro-inflammatory cytokines TNF-α and IL-6." (PMID 24979131, 2014). "Increased BMI is known to be associated with elevated CRP levels, and obesity has also been reported to affect cytokine levels and, therefore, only subjects with BMI in the range 18-30 were included in the study." (PMID 24669872, 2014). "High-sensitivity CRP is a more sensitive inflammatory marker associated with obesity indices than IL-6 and TNF-α." (PMID 24507240, 2014). "In this study, we describe the method for separating CRP-mfs from whole plasma and the associations of CRP mf-4 with obesity." (PMID 25299074, 2014). "The different BMI quartiles were then compared in order to further evaluate the association between obesity and levels of CRP and leptin." (PMID 24944619, 2014). "We found that the TREC number was inversely associated with levels of obesity indicators (BMI, hemoglobin A1c) and serum CRP levels." (PMID 24651652, 2014). "A new epidemiological study showed that obesity is associated with greater depressive symptoms and that CRP concentrations were independently associated with depression scores in analyses fully adjusted for sociodemographic and background variables." (PMID 24109426, 2013). "Several studies showed the association of adiposity or obesity with CRP was stronger in women than men." (PMID 24371525, 2013). "High levels of CRP are strongly associated in epidemiological studies with obesity, cardiovascular disease, MS, IR, increased FPG, and T2DM." (PMID 23367494, 2013).
Obesity (continued). "Over the 2‐year follow‐up, higher baseline hs‐CRP levels were associated with a significant increase in BMI z‐score (P<0.001) and significantly higher risk of incident overweight/obesity." (PMID 23744403, 2013). "In summary, we confirmed the association between hs‐CRP and higher body mass and overweight/obesity risk in a large population of European children." (PMID 23744403, 2013). "C-reactive protein has been associated with obesity in both adults and children and with an increase of cardiovascular risk factors and metabolic syndrome." (PMID 24335710, 2013). "Our findings also suggested that the association between CRP and metabolic syndrome are largely explained by obesity." (PMID 24069195, 2013). "Regarding to gender, women normally have significantly higher CRP levels than men and stronger correlation was found in women between the association of obesity and CRP level." (PMID 23484158, 2013). "Since the adipose tissue, particularly from visceral fat depots, is capable of producing pro-inflammatory cytokines that induce hepatic production of CRP and other acute phase proteins, it is plausible that the association observed is mediated by obesity." (PMID 22426755, 2013). "The summary evidence from previous studies is that a consistent association exists between obesity and increased CRP levels in children." (PMID 23744403, 2013). "Obesity is recognized as being associated with a chronic, low-grade, inflammation, with altered levels of several circulating factors such as C-reactive protein (CRP), tumor necrosis factor α (TNF-α), and interleukin-6 (IL-6)." (PMID 23409006, 2013). "Whereas cross‐sectional studies have shown that obesity is associated with increased C‐reactive protein (CRP) levels in children, little is known about the impact of low‐grade inflammation on body mass changes during growth." (PMID 23744403, 2013). "Individuals with obesity are at increased risk for various chronic diseases, several of which are also characterized by elevated CRP concentrations." (PMID 23690772, 2013). "Levels of IL-6 correlate with weight, BMI, waist/hip circumference, waist/hip ratio, and CRP concentration implicating this cytokine in obesity-associated inflammation." (PMID 23819063, 2013). "Our findings indicate that the mechanisms linking cardiorespiratory fitness, MetS risk, and CRP are extensively affected by obesity." (PMID 22315623, 2012). "Metformin has been shown to reduce obesity-associated inflammation and other inflammatory responses, and it reduces serum C-reactive protein levels in women with polycystic ovary syndrome." (PMID 22837425, 2012). "Among the variables used to assess CVD risk, obesity and elevated fasting glucose were each significantly associated with higher CRP (β = 2.310, t = 2.302, P = 0.028 and β = 2.396, t = 2.091, P = 0.045, resp)." (PMID 22461977, 2012). "Obesity is related to increased level of inflammatory markers such as CRP (C-reactive protein) that are associated with metabolic syndrome." (PMID 23213569, 2012). "Two such factors include leptin and C-reactive protein (CRP), and both are associated with indices of obesity and cardiovascular disease." (PMID 22533665, 2012). "Obesity is strongly associated with elevated concentrations of circulating markers of inflammation, such as CRP." (PMID 22691465, 2012). "The study provides initial support for a possible association between poor CRF and/or overweight/obesity and inflammatory status in children, based on elevated salivary CRP levels." (PMID 23108518, 2012). "Obesity is a risk factor for cardiovascular disease and has influence on serum levels of biomarkers e.g. CRP, cholesterol and it is associated with hypertension." (PMID 23095712, 2012). "While obesity is related to higher levels of CRP, following weight loss reduction in CRP levels has been also reported." (PMID 22649299, 2012).
Obesity (continued). "The tumor necrosis factor-α (TNF-α) SNP at position -308 G/A has been associated with obesity risk and increased C-reactive protein (CRP) concentrations." (PMID 23176569, 2012). "Smoking during pregnancy was a significant risk factor for obesity (OR 2.22, 95% CI, 1.13–2.83), overweight (OR 1.79, 95% CI 1.13–2.83), and highest quintile of CRP (OR 1.63, 95% CI, 1.05–2.51) among NHW." (PMID 22685478, 2012). "In line with a previous report in children and young adults, we found that the association between cardiorespiratory fitness and CRP was largely explained by their interrelation to obesity." (PMID 22315623, 2012). "CRP levels are also reported to associate positively with BMI, suggesting that CRP is a useful biomarker for obesity-linked chronic inflammatory states." (PMID 22216303, 2011). "It is now well established that obesity is characterised by chronic inflammation, with associated increases of CRP, interleukin-6 (IL-6) and plasminogen activator inhibitor." (PMID 21081932, 2011). "Obesity is associated with a low grade inflammation with slightly elevated serum levels of acute phase proteins including C-reactive protein (CRP) and serum amyloid A (SAA)." (PMID 21611116, 2011). "Other studies, however, demonstrated that the association between CRP and insulin resistance was obesity dependent in healthy population." (PMID 21167068, 2010). "Since both increased levels of CRP and fibrinogen were associated at baseline with increased BMI, the possibility that obesity plays a critical role in the lung function–systemic inflammation relationship remains a clear possibility." (PMID 20625390, 2010). "As with classic inflammatory conditions, obesity is associated with elevated levels of the acute phase reactant C-reactive protein (CRP)." (PMID 20178593, 2010). "In this study we demonstrated that obesity and insulin resistance were strongly associated with CRP." (PMID 21167068, 2010). "Several studies have reported that both GGT and CRP synergistically increase with the risk of both metabolic syndrome and obesity as well as with a high alcohol intake." (PMID 20920226, 2010). "We compared CRP levels in Indigenous Australians and the general population, accounting for obesity and other risk factors." (PMID 21078191, 2010). "We also found significant gender difference in the association of metabolic syndrome with hs-CRP after stratification according to the status of insulin resistance, obesity, microalbuminuria, cardiovascular risk, and arteriosclerosis." (PMID 20663138, 2010). "First, some studies have shown that reductions in CRP levels were strongly correlated with the amount of weight loss, suggesting a direct link between CRP and obesity." (PMID 21076541, 2010). "The aim of this study was to investigate the relation between C-reactive protein (CRP) with physical fitness, physical activity, obesity, and selected cardiovascular risk factors in school-children." (PMID 21566779, 2010). "There are, however, few data about the association between obesity, physical activity and serum CRP concentrations in black South African children." (PMID 21135979, 2010). "The mechanisms responsible for the association between obesity and CRP are not yet clearly understood." (PMID 21566779, 2010). "Recent studies have been confirming the positive association between obesity indices and inflammatory markers, mainly CRP protein in women, but also other inflammatory markers, both in women and men." (PMID 20706689, 2010). "The purpose of this study was to investigate the relation between CRP with physical fitness, physical activity, obesity, and selected cardiovascular risk factors in schoolchildren." (PMID 21566779, 2010). "Still, few data regarding CRP, obesity and CVD risk have been generated for minority populations, and no information is available for CRP and related variables for Cuban-Americans, either healthy or dysmetabolic." (PMID 20617007, 2010).